CD96 (CD96 molecule)
Diseases named in the same sentence as CD96 in open-access papers (continued):
Sharing a sentence is not in itself a finding about the gene and the disease.
liver cancer (4 papers, 2021 to 2022). An epithelial or non-epithelial malignant neoplasm that arises from the liver. "In liver cancer, high expression of CD96 is closely associated with deterioration and shorter disease-free survival (DFS) and OS times in patients, and it is accompanied by a low efficacy of antitumor immunotherapy." (PMID 35646934, 2022). "Another study indicated that the high expression of CD155 in liver cancer could induce NK cells to up-regulate CD96, leading to impaired NK cell function and inhibition of survival, which is associated with poor clinical prognosis of patients with liver cancer." (PMID 35433470, 2022). "Blocking the CD96-CD155 axis or TGF-β1 restores NK cell function by reversing NK cell exhaustion, suggesting a possible therapeutic role of CD96 in fighting liver cancer." (PMID 33946954, 2021). "On the one hand, in CD96−/− mice displaying hypersensitive NK-cell responses to immune challenge and significant tumor resistance, blocking CD96−CD155 interaction or TGF-β1 restores NK cell immunity against tumors by reversing NK cell exhaustion in liver cancer." (PMID 34925438, 2021).
Sepsis (4 papers, 2022 to 2026). Sepsis is defined as life-threatening organ dysfunction caused by a dysregulated host response to infection. "Currently, there are many biomarkers used in the prediction of sepsis prognosis, such as CD247, FYN, CD96, etc., most of which have been studied individually as single biomarkers." (PMID 38755528, 2024). "Our results suggest that CD96 and SAMD3 were located on T cells and down-regulated in sepsis group, which were positively correlated with survival rate." (PMID 36918563, 2023). "BCL9L, BCL11B, CD247, CD96 and SAMD3 were decreased in sepsis and mainly expressed in the T cell; while MAFG increased in sepsis and localizes to monocytes." (PMID 36918563, 2023). "The expression results of core genes in different samples showed that five genes (BCL9L, BCL11B, CD96, SAMD3 and CD247) were decreased in sepsis samples, compared with the normal group." (PMID 36918563, 2023).
skin cutaneous melanoma (4 papers, 2021 to 2023). "CD96 was clearly upregulated in skin cutaneous melanoma patients and carried out its effects through regulating several signaling pathways, containing the JAK-STAT, PI3K-Akt, and MAPK." (PMID 36043142, 2022). "According to TCGA, GTEx, and gene expression profile interaction analysis dataset in this paper, compared with normal skin tissues, CD96 was expressed at higher levels in human cutaneous melanoma skin tissues." (PMID 36043142, 2022). "Our findings showed that CD96 may serve as a new gene for the diagnosis and treatment of skin cutaneous melanoma patients." (PMID 36043142, 2022). "Abnormally expressed CD96 was significantly related to the stage of skin cutaneous melanoma." (PMID 36043142, 2022). "In conclusion, our study demonstrated a higher expression level of CD96 in cutaneous skin melanoma." (PMID 36043142, 2022). "As in cutaneous melanoma, the anti-MAA clonotypes formed frequent inhibitory interactions with tumor cells via PVR – TIGIT/CD96 and with immune cells via Galectin 9 – TIM3." (PMID 36220826, 2022).
colon cancer (3 papers, 2021 to 2023). "We tested the therapeutic potential of an anti-CD96 antibody alone or in combination with an anti-PD-1 antibody in a mouse colon cancer model." (PMID 36140247, 2022). "We carried out an in vivo tumor therapy study in an MC-38 mouse colon cancer model using mAbs to target PD-1 and CD96." (PMID 36140247, 2022). "Here, we studied the effect of anti-CD96 alone and in combination with anti-PD-1 on tumor growth in the mouse colon cancer model MC-38." (PMID 36140247, 2022). "Together, we were able to corroborate previous findings of PD-1 and CD96 co-inhibition on the TILs composition in murine colon tumor models." (PMID 36140247, 2022). "This suggests that the anti-CD96 and anti-PD-1 antibodies induced considerably different amounts of ADAs, indicating that the mAbs triggered very different extents of immunogenicity in the mouse colon cancer model." (PMID 36140247, 2022).
head and neck squamous cell carcinoma (3 papers, 2021 to 2022). A squamous cell carcinoma that arises from any of the following anatomic sites: lip and oral cavity, nasal cavity, paranasal sinuses, pharynx, larynx, and salivary glands. "Furthermore, CD96 expression correlated with survival in HPV+ head and neck squamous cell carcinoma, and its cross-linking activated tumor-infiltrating T cells, thus highlighting the potential of anti-CD96 antibodies in cancer immunotherapy." (PMID 35998045, 2022). "CD96 expression was significantly elevated in various cancer types, including esophageal carcinoma (ESCA), head and neck squamous cell carcinoma (HNSC), kidney renal clear cell carcinoma (KIRC), kidney renal papillary cell carcinoma (KIRP), and stomach adenocarcinoma (STAD)." (PMID 33680972, 2021). "Using publicly available data from The Cancer Genome Atlas database through the Tumor Immune Estimation Resource, we first investigated the effect of CD96 expression on the survival of patients with HPV+ or HPV– head and neck squamous cell carcinoma (HNSCC)." (PMID 35998045, 2022).
HIV-1 infection (3 papers, 2012 to 2025). The type species of lentivirus and the etiologic agent of acquired immunodeficiency syndrome (AIDS). "Considering that chronic disease-associated alteration in CD96 has already been observed during Hepatitis B infection, we aimed to investigate changes in expression of CD96 during HIV-1 infection, a receptor with potential importance for effector functions." (PMID 23272144, 2012). "Next, the ability of Vpu to down-regulate CD96 was analyzed in the context of HIV-1 infection and compared to other established Vpu functions such as the down-regulation of CD4 and CD317 (Tetherin)." (PMID 40911682, 2025). "Correspondingly, we observed that CD96 expression was decreased during chronic HIV-1 infection in our cohort." (PMID 23272144, 2012). "All together these results show that even though CD96 is considered a T cell activation marker, HIV-1 infection, in particular uncontrolled infection, appears to promote down-regulation of CD96 expression." (PMID 23272144, 2012). "We investigated the effect of HIV-1 infection on the expression of CD96, which is also called T cell ACTivating Increased Late Expression (TACTILE)." (PMID 23272144, 2012). "Although treatment with LC also impaired the ability of HIV-1 to down-regulate CD96 from the cell surface, it is difficult to clearly conclude on this, since LC interfered with productive HIV-1 infection, was slightly cytotoxic, and reduced CD96 cell surface levels also in uninfected CD4+ T cells." (PMID 40911682, 2025). "We have shown that during HIV-1 infection the CD8+ T cell population express lower levels of CD96." (PMID 23272144, 2012). "All together, these data suggest that changes in CD96 expression may be a useful additional marker to measure overall effector function and disease progression during HIV-1 infection." (PMID 23272144, 2012). "Although CD155, as the ligand of TIGIT, CD226 and CD96, is rarely expressed on CD4 T cells, it was upregulated in acute and chronic HIV-1 infection." (PMID 33717085, 2021). "Contrary to the upregulated TIGIT expression on NK cells, CD96, which shares the ligand of CD155 with CD226 and TIGIT, was upregulated on NK cells in both acute and chronic HIV-1 infection." (PMID 33717085, 2021). "Overall, CD96 did neither influence WT HIV-1 infection rate nor that of the vpu- and nef-deleted virus devoid of active CD96 down-regulation." (PMID 40911682, 2025). "In this study, we demonstrated the dynamics of TIGIT, CD96 and CD226 expression and functions in NK cells in the first, third and twelfth month after HIV-1 infection in our Beijing PRIMO clinical cohort and chronic HIV-1 individuals with over 2 years of infection." (PMID 33717085, 2021). "In this study, CD96−CD226+ cells in total NK cells including TIGIT+NK and TIGIT−NK cells significantly diminished, while CD96+CD226− cells expanded at all the acute and chronic phases of HIV-1 infection, which indicated that the expression of these two NK subset cells were oppositely affected." (PMID 33717085, 2021). "CD96 has not previously been studied in the context of HIV-1 infection, but due to its potential importance in immune regulation and relevance to chronic disease, we examined CD96 expression in relation to HIV-1 pathogenesis." (PMID 23272144, 2012). "Furthermore, despite the close relationship and similar characteristics of CD96 and CD226, they are differentially affected by HIV-1 infection." (PMID 23272144, 2012). "We have established that the frequency of CD96 expression is modified during HIV-1 infection and that the density of CD96 per cell is decreased in non-controllers suggesting that cells lacking CD96 may potentially be dysfunctional." (PMID 23272144, 2012). "The expression of CD96 during HIV-1 infection has not previously been assessed, but based on reports that CD96 is up-regulated during T cell activation we hypothesized that CD96 would be higher in HIV-1 patients due to persistent immune activation." (PMID 23272144, 2012).
HIV-1 infection (continued). "Furthermore, modulations in CD96 expression during disease such as HIV-1 infection and relationship to pathogenesis has not previously been reported." (PMID 23272144, 2012).
lung adenocarcinoma (3 papers, 2021 to 2024). A carcinoma that arises from the lung and is characterized by the presence of malignant glandular epithelial cells. "On the contrary, CD96 was low expressed in lung adenocarcinoma (LUAD), LUSC, READ, and THCA compared to GTEx normal controls." (PMID 33680972, 2021).
myelodysplastic syndrome (3 papers, 2022 to 2023). A clonal hematopoietic disorder characterized by dysplasia and ineffective hematopoiesis in one or more of the hematopoietic cell lines. "CD96 expression has also been noted in various hematological malignancies, such as T-ALL, myelodysplastic syndrome (MDS), and leukemic stem cells (LSCs) in AML." (PMID 35812451, 2022).
ovarian carcinoma (3 papers, 2018 to 2025). A malignant neoplasm originating from the surface ovarian epithelium. "CD96 has been proved the key for natural killer (NK) cell reactivity to advanced ovarian cancer." (PMID 35756990, 2022). "For advanced ovarian cancer, researchers have thoroughly investigated the regulatory mechanisms of the DNAM-1/TIGIT/CD96 signaling axis in NK cell-mediated antitumor immune responses." (PMID 40463500, 2025). "In ovarian cancer, down-regulation of DNAM-1 and up-regulation of CD96, an inhibitory receptor, lead to the emergence of functionally suppressed and exhausted phenotypes in NK cells." (PMID 40463500, 2025).
autoimmune disease (2 papers, 2022 to 2023). A disorder resulting from loss of function or tissue destruction of an organ or multiple organs, arising from humoral or cellular immune responses of the individual to their own tissue constituents. "The PVR/TIGIT/CD226/CD96 signalling axis represents a promising therapeutic target for both cancer immunotherapy and the treatment of autoimmune diseases." (PMID 36944702, 2023). "IRs, including CTLA4, PD1, LAG3, TIM3, TIGIT, and CD96, play a certain role in the pathogenesis of autoimmune diseases." (PMID 35769669, 2022). "CD96 was identified in 1992 and found to be involved in some autoimmune diseases." (PMID 35769669, 2022). "CD4 T cells play a major role in the pathogenesis of autoimmune diseases, and the function of CD96 in CD4 T cells has not yet been reported." (PMID 35769669, 2022).
colon adenocarcinoma (2 papers, 2021 to 2023). "In endocervical adenocarcinoma, colon adenocarcinoma, and esophageal cancer, the Estimatescores strongly correlates with CD96 abundance." (PMID 36674817, 2023). "However, the expression of CD96 in breast invasive carcinoma (BRCA), colon adenocarcinoma (COAD), lung squamous cell carcinoma (LUSC), rectum adenocarcinoma (READ), SKCM, and thyroid carcinoma (THCA) was significantly decreased." (PMID 33680972, 2021).
esophageal squamous cell carcinoma (2 papers, 2024). Esophageal squamous cell carcinoma (ESCC) is a type of esophageal carcinoma (EC) that can affect any part of the esophagus, but is usually located in the upper or middle third. "Notably, studies using disulfidptosis scores have identified the CD96 gene as an independent prognostic marker for esophageal squamous cell carcinoma (ESCC)." (PMID 38292868, 2024). "Research indicates that the disulfidptosis-related genes CD96 and SOX17 could potentially act as independent prognostic factors in patients with esophageal squamous cell carcinoma (ESCC)." (PMID 38685115, 2024).
Hepatitis B (2 papers, 2012 to 2017). "It has already been reported that CD96 can be shed during chronic disease such as Hepatitis B infection." (PMID 23272144, 2012). "Furthermore CD96 plays a key role in chronic viral disease induced by Hepatitis B or HIV-1, where investigations could reveal that CD96 expression is pathogenetically linked to disease progression." (PMID 28073373, 2017).
low grade glioma (2 papers, 2019 to 2020). A grade I or grade II glioma arising from the central nervous system. "CD155 can form the same complex with CD96, CD226, AFDN, ITGAV, ITGB3, and AFDN in low-grade glioma (LGG) and GBM samples derived from the Biological Pathway Ex-change (BioPAX)." (PMID 31377744, 2019).
lymph node metastasis (2 papers, 2016 to 2024). "Further analysis demonstrated that the decrease in the percentage of CD226+ and CD96+ NK cells was associated with tumor histological grade and lymph node metastasis." (PMID 27626490, 2016). "Further, tumors with lymph node metastasis had a significantly higher percentage of CD96+ NK cells than tumors without lymph node metastasis." (PMID 27626490, 2016).
oral cancer (2 papers, 2023 to 2024). "The current study shows increased CD96 mRNA and protein expression in oral cancer tissue compared to the healthy oral mucosa." (PMID 37046787, 2023). "The increased expression of CD96 in OSCCs shown by the current study also motivates the investigation of anti-CD96 therapy in oral cancer." (PMID 37046787, 2023). "This indicates that the direct tumor cell-bound expression of CD96 might also be relevant in oral cancer." (PMID 37046787, 2023). "Therefore, the value of CD96 expression for a multi-marker liquid biopsy for oral cancer should be evaluated." (PMID 37046787, 2023). "In addition, CD96 expression in OSCC tissue was positively associated with PD1 and PD-L1 which are important ICPs in oral cancer and are used successfully in immune therapy." (PMID 37046787, 2023). "The significant positive correlation between BTLA expression and other immune checkpoints including CD96 and PD1 with its ligands indicate that BTLA-inhibition in oral cancer might be promising, especially in the form of a combination immunotherapy." (PMID 38928307, 2024). "Hence, the data highlight the expression of BTLA in oral cancer and motivate clinical trials of anti-BTLA therapy—preferentially as a concept of a simultaneous therapeutic targeting of multiple inhibitory signalling pathways like PD1, CD96 and BTLA—in oral cancer." (PMID 38928307, 2024).
prostate carcinoma (2 papers, 2019 to 2023). A carcinoma that arises from epithelial cells of the prostate gland. "In prostate cancer tissue, high CD96 gene expression was significantly associated with disease recurrence." (PMID 37046787, 2023).
psoriasis (2 papers, 2022 to 2023). An autoimmune condition characterized by red, well-delineated plaques with silvery scales that are usually on the extensor surfaces and scalp. "While TIGIT has been described as an important indicator of disease severity in psoriasis, our results cannot rule out that the early protective effect of vdPVR could, in part, be mediated through CD96 and that the action of vdPVR-Fc may not be fully restricted to T-cells alone." (PMID 36944702, 2023).
uveal melanoma (2 papers, 2021 to 2025). A melanoma derived from melanocytes of the uveal tract. "Elevated CD96 expression was significantly related to a poorer OS in GBM (HR = 1.28, 95% CI = 1.04–1.58, P = 0.020), LGG (HR = 2.18, 95% CI = 1.79–2.66, P = 1.5e-14), and uveal melanoma (UVM; HR = 1.33, 95% CI = 1.08–1.63, P = 0.007)." (PMID 33680972, 2021). "Additionally, concerning immunosuppressive gens, PLAG1 was significantly positively correlated with TIGIT, CD96, and CD244 in LGG, uveal melanoma, and liver hepatocellular carcinoma, indicating that it may facilitate the formation of a tumor immune-suppressive microenvironment." (PMID 40276502, 2025).
viral infection (2 papers, 2022). "In contrast, the exhausted genes were up‐regulated after viral infection (e.g. Havcr2, Lag3, Cd96 and Ctla4)." (PMID 35051311, 2022).
abortion (1 paper, 2023). the ending of pregnancy by removing a fetus or embryo before it can survive outside the uterus. "The aims of this study were to investigate the role and molecular mechanism of CD96 in resident dNK cells during pregnancy, to investigate the influencing factors on the pathogenesis of spontaneous abortion, and to explore the function of palmitic acid in this process." (PMID 37760110, 2023). "The low expression of CD96 in spontaneous abortion patients indicates the enhanced activity of NK cells, which may be one of the possible factors contributing to pregnancy failure." (PMID 37760110, 2023).
anal carcinoma (1 paper, 2023). "Conversely, there were a number of productive immune genes contributing to ‘defense response’ in non-recurrent anal cancer isolates such as IL4, HLA-A, CD200R1, and CD96." (PMID 37177979, 2023).
Arthritis (1 paper, 2023). Inflammation of a joint. "Using an online Venn diagram tool, we then screened four genes related to dysregulated genes shared by TGT’s active ingredients and SLE and arthritis, including NLRC3, CD96, CCL2, and TLR1." (PMID 37312878, 2023).
asthma (1 paper, 2021). "It was also reported that anti-CD96 mAb treatment could inhibit established airway inflammation as effectively as dexamethasone pretreatment in a mouse model of asthma." (PMID 34336929, 2021).
brain tumors (1 paper, 2021). "For instance, in brain tumors (GBM and LGG), CD96 was only positively correlated with infiltration levels of CD8+ T cells, dendritic cells, macrophages, and neutrophils, partially due to the distinct tumor microenvironments in central nervous system." (PMID 33680972, 2021).
breast tumors (1 paper, 2021). "NECTIN2 and NECTIN4 secreted by BCSC interacted with CD96 and TIGIT on immune cells, causing T-cell inhibition and immune escape at primary breast tumors." (PMID 34611125, 2021).
C syndrome (1 paper, 2017). "Given the uncertain role of CD96 in OTCS MAGEL2 might be the first gene clearly associated with Opitz C syndrome." (PMID 28281571, 2017).
cerebral cavernous malformation (1 paper, 2012). A disorder characterized by malformations in the structure of the capillaries in the brain. "We observed that “Generic Binding Proteins” were enriched in the MapsloBTlo region of the graph and corresponded to weakly connected genes; examples at the lowest end (Maps = 1, BT = 0) include CCM2 (cerebral cavernous malformation 2), CD96, and CDH17 (liver-intestine cadherin)." (PMID 22548703, 2012).
chronic Hepatitis B infection (1 paper, 2012). "The clinical significance of CD96 is still comparatively limited although it has been associated with chronic Hepatitis B infection and disease progression." (PMID 23272144, 2012).